ZBTB20 (zinc finger and BTB domain containing 20)
Diseases named in the same sentence as ZBTB20 in open-access papers (continued):
Sharing a sentence is not in itself a finding about the gene and the disease.
prostate tumors (1 paper, 2018). "We found that the LSAMP gene that is frequently deleted in ERG-negative prostate tumors of African American men49, was often rearranged including fusion with ZBTB20 specifically in the ERG-negative group." (PMID 30150711, 2018).
triple-negative breast carcinoma (1 paper, 2025). An invasive breast carcinoma which is negative for expression of estrogen receptor (ER), progesterone receptor (PR), and human epidermal growth factor receptor 2 (HER2). "Based on these findings, we hypothesize that targeting regulators of macrophage polarization, especially ZBTB20, may offer novel intervention targets for triple-negative breast cancer (TNBC) treatment." (PMID 40580873, 2025).
tumor (20 papers, 2011 to 2025). "A total of five apaQTL-SNPs (rs41301932, rs4494603, rs9890400, rs56066320, and rs41301932), located on RNF213, were significantly associated with LUAD risk (p < 0.05), and they inhibit tumor growth through ubiquitin-mediated degradation of ZBTB20." (PMID 39125654, 2024). "This is quite interesting since Zbtb20 overexpression is usually linked to a more malignant tumor phenotype." (PMID 37762065, 2023). "The positive expression of ZBTB20 was associated with large tumor size, high Edmondson-Steiner grading and advanced tumor-node-metastasis (TNM) tumor stage." (PMID 26893361, 2016). "Investigation of gene fusions caused by SVs identified; the well-established PCa fusion gene TMPRSS2-ERG in 10% and 33% of tumours from African and European patients, respectively; the previously reported African-specific ZBTB20-LSAMP; and nine novel African-associated fusions." (PMID 36045381, 2022). "The discovery that finasteride, an FDA-approved drug, can effectively reverse tumor-induced M2 polarization through upregulation of ZBTB20 represents a major advancement in repurposing existing therapeutics for cancer immunotherapy." (PMID 40580873, 2025). "miR‐129‐5p targets ZBTB20, and its inhibition reverses the effects of RPLP0P2 downregulation, while ZBTB20 overexpression counteracts miR‐129‐5p's tumor suppression." (PMID 40556338, 2025). "Through virtual molecular docking and deep learning-based drug synergy prediction, we identified finasteride as a novel ZBTB20-targeting agent capable of reversing tumor-induced M2 polarization." (PMID 40580873, 2025). "Computational pharmacology identified finasteride as a ZBTB20 modulator (binding energy:7.7 kcal/mol) capable of reversing tumor-induced M2 macrophage polarization." (PMID 40580873, 2025). "Last but not least, considering the close link between ZBTB20 and immune regulation in scenarios of both health and cancer, ZBTB20 is possibly involved in the regulation of host immune surveillance and tumor microenvironment." (PMID 38397429, 2024). "The LncRNA SNHG8, which shows low expression in tumor tissues, represses the synthesis of miR-634 and thus disinhibits the Zbtb20 signaling pathway." (PMID 37762065, 2023). "A recent study provided a glimpse into the role of Zbtb20 in tumor immunity and showed that deleting Zbtb20 enhances the anti-tumor activity of CD8+ cytotoxic T cells." (PMID 37762065, 2023). "In both cases, overexpressing these miRs leads to decreased Zbtb20 protein levels and lower proliferation of the respective tumor cell cultures." (PMID 37762065, 2023). "Tumor growth cures, generated over 21 days, revealed that ZBTB20 overexpression promoted tumor growth of SMMC-7721 cells in mice." (PMID 26893361, 2016). "As expected, SETD7, H3K4me2, CDKN2D, and ZBTB20 are significantly higher in HCC tumor tissues than in ANLTs." (PMID 27183310, 2016). "We observed that increased expression of ZBTB20 in HCC was positively correlated with tumor vein invasion, recurrence and metastasis." (PMID 21702992, 2011). "It was showed that ZBTB20 staining was mainly in the nucleus of tumor cells, partly in the cytoplasm." (PMID 21702992, 2011). "Both messenger RNA and protein expression levels of ZBTB20 were elevated significantly in HCC tissues compared with the paired non-tumor tissues and normal liver tissues." (PMID 21702992, 2011). "Consistent with mRNA expression, the protein level of ZBTB20 in HCC tumor tissues was also significantly higher than that in NT samples (1.81-fold on average, P < 0.001)." (PMID 21702992, 2011). "Our data revealed that both mRNA and protein levels of ZBTB20 were significantly higher in HCC tissues than in the corresponding non-tumor tissues and normal liver tissues." (PMID 21702992, 2011). "Likewise, ZBTB20 was further identified to exert a tumor-promoting role in AML cells via the circ-0001602/miR-192-5p/ZBTB20 axis." (PMID 38397429, 2024).
tumor (continued). "PFKP was also positively associated with tumor diameter and extrascleral extension whereas the tumors with ZBTB20 deficiency exhibited a more diffuse rather than focal pattern of macrophage infiltration." (PMID 38673877, 2024). "Intriguingly, memory CD8+ T cells lacking Zbtb20 confer superior protection against tumors compared to wild-type (WT) memory cells, suggesting that deletion or inhibition of Zbtb20 in CD8+ T cells may provide a promising strategy for anti-tumor immunotherapy." (PMID 38397429, 2024). "So far, we presented the effect of Zbtb20 on cell biology in the context of a tumor environment." (PMID 37762065, 2023). "LSAMP was identified as a new potential driver gene in this study; other studies also reported a significantly higher number of inter-chromosomal rearrangements and exclusive association of LSAMP deletion/rearrangement for African American tumours, including ZBTB20-LSAMP gene fusion." (PMID 36045381, 2022). "Transcriptional profiling of such a large cohort of a single molecular type of cancer allows for a thorough understanding of the tumor’s genomic landscape, including the identification of genes affected by mutations (GNAS, MYCN, PPM1D, and PRKAR1A), and fusion transcripts (ZBTB20 and NCOR1)." (PMID 33741928, 2021). "However, we corroborated the tumor-suppressive roles of insertions in Adk and Zbtb20 and in Nipbl, Pdlim5, Ppp1r12a, Tnrc6b, Brd4, Cul3, Ctnna3, Elavl1, Gphn, Nfia, Ptpn12, Taok3, and Rasa1." (PMID 33435458, 2021). "At the same time, ZBTB20 has a high degree of homology with BCL6 protein, and plays an important regulatory role in hematopoiesis, immune response and tumor development, and some studies have clarified the regulatory effect of ZBTB20 on gastric migration, invasion and proliferation of GC." (PMID 32936247, 2020). "Both VDR and ZBTB20 were previously shown to operate as tumor suppressors in cancer." (PMID 32855526, 2020). "Besides, a recent study has found that zinc finger protein ZBTB20 promotes tumor growth of HCC via transcriptionally repressing FoxO1." (PMID 28637446, 2017). "Collectively, these results indicate that ZBTB20 may serve as a prognostic marker and promotes tumor growth of HCC via transcriptionally repressing FoxO1." (PMID 26893361, 2016). "Moreover, expression of ZBTB20 was assessed by immunohistochemistry of paired tumor and peritumoral liver tissue from 102 patients who had undergone hepatectomy for histologically proven HCC." (PMID 21702992, 2011). "The close relationship between ZBTB20 expression and clinicopathological features predicted that ZBTB20 might boost carcinogenesis and tumor progression." (PMID 21702992, 2011). "This makes Zbtb20 a valuable marker for suspected HCC in the preoperative biopsy, where only small tumor fragments are sent for histopathological evaluation." (PMID 37762065, 2023). "ZBTB20 can act as a transcriptional repressor of FOXO1 to promote cell proliferation and tumor growth." (PMID 32375413, 2020). "Clinical association analysis using a Pearson chi-squared test revealed that the expressions of ZBTB20 were evidently higher in HCC patients with large tumor size (P = 0.010), high Edmondson-Steiner grading (P = 0.042) and advanced TNM tumor stage (P = 0.010)." (PMID 26893361, 2016). "In the present study, our data showed that increased expression of ZBTB20 was obviously correlated with large tumor size, high Edmondson-Steiner grading and advanced TNM tumor stage in HCC." (PMID 26893361, 2016). "Positive expression of ZBTB20 was detected in 82 (63.1%) of the HCC specimens, whereas only 42 (32.3%) of the normal tumor-adjacent tissues showed a positive ZBTB20 signal (P < 0.01)." (PMID 26893361, 2016). "We found that the levels of ZBTB20 mRNA and protein in HCC tissues were significantly higher than those in matched normal tumor-adjacent tissues (P < 0.01)." (PMID 26893361, 2016).
tumor (continued). "Furthermore, ZBTB20 proved to be a risk factor for tumor recurrence and independent molecular marker of prognosis in HCC and may become a novel molecular target in the strategies for the prediction of tumor recurrence and prognosis or treatment of HCC." (PMID 21702992, 2011). "This suggests that its targets, such as SH3BP5, NBEA, ZBTB20, ESR2, and ESR1, may escape miR-204-mediated repression, potentially leading to their overexpression, which could promote tumor growth and metastasis." (PMID 41009685, 2025). "Our analysis identified that ZBTB20 modulates 1197 genes in B cells, influencing processes such as protein dephosphorylation, stress response, NF‐κB signalling and TOR signalling pathways, thereby reinforcing its pro‐tumour function." (PMID 41275425, 2025). "Of interest, ZBTB20 triggers increased production of IFN-α in MCL cells upon BACH1 silencing, indicating that ZBTB20 is very likely to participate in the BACH1-mediated regulation of the tumor immune microenvironment." (PMID 38397429, 2024). "Furthermore, Zbtb20 is regulated by interactions with a myriad of long non-coding RNAs (lncRNAs), circular RNAs, and miRs, so direct mutation to the gene could be absent in the tumor tissue, but its expression can still be dysregulated." (PMID 37762065, 2023). "The mRNA level of ZBTB20 was significantly higher in 38 (76%) HCC tissues (tumour; T) compared with the pair-matched non-tumor tissues (NT)." (PMID 21702992, 2011). "However, ZBTB20 and AFP expression, both of tumor tissue origin, were really inversely related." (PMID 21702992, 2011). "Meanwhile, tumor size, serum AFP, TNM stage, tumor number and vein invasion were all independent prognostic factors for OS; while tumor size, HBsAg positive, TNM stage, tumor number, vein invasion and peritumoral ZBTB20 expression were independent prognostic factors for DFS." (PMID 21702992, 2011).
cancer (16 papers, 2016 to 2025). A tumor composed of atypical neoplastic, often pleomorphic cells that invade other tissues. "For example, what is the function of ZBTB20 variants in cancer cells?" (PMID 38397429, 2024). "In addition, many ZBTB20 variants have been identified in some cancers, but the pathogenic mechanisms are poorly understood." (PMID 38397429, 2024). "The molecular mechanisms and interactions of ZBTB20 within cellular systems should be further explored to better understand its central role in cancer regulation and its potential as a therapeutic target." (PMID 40497236, 2025). "Of note, more attention should be paid to the epigenetic modifications of the ZBTB20 gene in cancer cells since the gene expression of ZBTB20 is differentially downregulated in HCC cells after knockdown of histone lysine methyltransferase SETD7." (PMID 38397429, 2024). "In this case, we summarize the known mechanisms and potential functions of ZBTB20 in different cancers." (PMID 38397429, 2024). "Given the diverse functions of ZBTB20 in both health and disease, we herein summarize the structure and physiological roles of ZBTB20, with an emphasis on the latest findings on tumorigenesis and cancer progression." (PMID 38397429, 2024). "To date, there have been many unresolved issues related to the dysregulation of gene transcription and the mechanisms underpinning complex regulatory network in human cancers; ZBTB20 is one of them." (PMID 38397429, 2024). "As such, we summarize the structure and physiological function of ZBTB20, with a particular focus on its roles in human cancers and potential therapeutic implications." (PMID 38397429, 2024). "In this context, it will be of tremendous interest to explore the upstream and downstream regulatory network of ZBTB20 in cancer cells." (PMID 38397429, 2024). "ZBTB20 has also been increasingly identified as a key regulator in the pathogenesis and development of human cancers." (PMID 38397429, 2024). "In terms of ZBTB20 WT protein, how is it transcriptionally or epigenetically regulated in cancer cells?" (PMID 38397429, 2024). "These two studies give us a glimpse of a possible pathway in the pathogenesis of malignant tumors where Zbtb20 expression is modulated by chronic inflammatory stress." (PMID 37762065, 2023). "The migration of human cancer cell lines has been assessed in conditions where Zbtb20 was overexpressed or silenced." (PMID 37762065, 2023). "Research into the function of ZBTB20 on different types of cancer cells has revealed that in tumors, ZBTB20 positively regulates migration, tissue invasion, and proliferation." (PMID 36140727, 2022). "Among these TFs, ZBTB20 has been reported to increase the malignancy of various cancers." (PMID 41275425, 2025). "On the other hand, ZBTB20, as well as being a TF, is itself concurrently modulated by different types of non-coding RNAs (e.g., lncRNA, circRNA, and miRNA) and other TFs, highlighting the complexity of ZBTB20-involving regulation in cancer cells." (PMID 38397429, 2024). "Interestingly, multiple lines of evidence from mice and human systems have revealed the importance of ZBTB20 in the pathogenesis and development of cancers." (PMID 38397429, 2024). "ZBTB20 is not only a hotspot of genetic variation or fusion in many types of human cancers, but also a key TF or intermediator involving in the dysregulation of cancer cells." (PMID 38397429, 2024). "Thus, Zbtb20 seems to help cells evade physiological apoptotic responses and speed up cancer propagation." (PMID 37762065, 2023). "Here we review the current data connecting Zbtb20 with malignant tumors." (PMID 37762065, 2023). "The gene Zbtb20 (also named DPZF, HOF or ZNF288) encodes a TF, belonging to the POK-family of BTB zinc finger transcriptional repressors, implicated in developmental processes and cancer." (PMID 27282384, 2016).
cancer (continued). "In non-small cell lung cancer (NSCLC), ZBTB20 is upregulated in NSCLC tissues, and it promotes cancer cell proliferation by repressing FOXO1." (PMID 38397429, 2024). "For example, one of the most common liver metastatic malignancies, GAC, also shows a nuclear reaction for an anti-Zbtb20 antibody." (PMID 37762065, 2023). "Therefore, we selected proteins that were significantly lower expressed in cancer both in the CPTAC Discovery study and the Chinese-LUAD study, and found that two of the predicted substrates, namely ZBTB20 and GLUD1, were lower in cancer." (PMID 39125654, 2024). "Regardless of the recent advances in understanding of ZBTB20 in cancers, there are still many unaddressed issues." (PMID 38397429, 2024).
infection (6 papers, 2016 to 2025). The state of being infected such as from the introduction of a foreign agent such as serum, vaccine, antigenic substance or organism. "In our previous work, we identified an association between Zbtb20 and regulation of metabolism in CD8 T cells responding to infection." (PMID 37414528, 2023). "After 72 h of infection with recombinant replication-deficient adenoviruses co-expressing ZBTB20 and EGFP (hereafter Ad-ZBTB20) at the MOI of 400, more than 85% of GH3 cells were green fluorescent protein-positive by flow cytometry assay." (PMID 27079169, 2016). "We identified ten NK subgroup-specific marker molecules (Kcnj8, Cmah, Ccnd2, Cx3cr1, Thy1, Tnfrsf9, Zbtb20, Gng11, CD226, Egr3) from C0 to C9 and assessed their expression changes during infection using RT-qPCR." (PMID 40244063, 2025).
neurodevelopmental disorder (6 papers, 2018 to 2026). A behavioral and cognitive disorder with onset during the developmental period that involves impaired or aberrant development of intellectual, motor, or social functions. "On another note, ZBTB20 has been previously implicated in influencing neurodevelopmental disorders in subjects of European ancestry." (PMID 34285142, 2021). "Here we show distinct effects of expression of two major isoforms, long and short, of ZBTB20, and its neurodevelopmental disorder-linked variants, on dendritic architecture of cultured rat cortical pyramidal neurons." (PMID 30281617, 2018). "Taken together, our study suggests ZBTB20’s role in dendritic and synaptic structure and provide possible mechanisms of its effect in neurodevelopmental disorders." (PMID 30281617, 2018). "Even though the genes AP4E1 and ZBTB20 have previously been linked to stuttering and separately to neurodevelopmental disorders, the mode of inheritance (i.e. dominance/recessivity) do not overlap." (PMID 40836029, 2026). "Similarly, ZBTB20, a transcription factor involved in synapses and neurodevelopmental disorders, has not been previously linked to addiction, although it did appear in a GWAS study on smoking initiation." (PMID 39766481, 2024). "We chose to include ZBTB20 as an exception, although it is neither a kinase, a GPCR, or an ion channel, because it was upregulated and thus constituted a possible desirable drug target, in addition to being linked to neurodevelopmental disorders." (PMID 37341859, 2023).
metabolic disorders (2 papers, 2017 to 2024). "Then we further examined the effects of Zbtb20 deficiency on HCD-induced metabolic disorders." (PMID 28327662, 2017).
cardiovascular diseases (1 paper, 2021). "Finally, we had reported that the injection of ZBTB20 knockdown adenovirus in the tail vein of ApoE−/− mice fed with a Western diet could alleviate AS, indicating that the tail vein adenovirus injection is a potential method for treatment of cardiovascular diseases." (PMID 34136067, 2021).
psychiatric disorder (1 paper, 2018). A disorder characterized by behavioral and/or psychological abnormalities, often accompanied by physical symptoms. "A number of candidate gene targets of ZBTB20 are worth noting, as they have been implicated in various psychiatric disorders and behavioral phenotypes." (PMID 30217971, 2018).
ZBTB20 also shares sentences with these, for which no sentence is quoted: Obesity (3 papers); diabetes (2); epilepsy (2); glioma (2); Insulin resistance (2); liver cancer (2); adenocarcinoma (1); adenoma (1); aging (1); Alzheimer disease (1); atherosclerosis (1); atrial fibrillation (1); Bosch-Boonstra-Schaaf optic atrophy syndrome (1); cardia (1); coronary artery disease (1); endothelial dysfunction (1); fibrosis (1); gastric adenocarcinoma (1); genetic disorder (1); gout (1); heart failure (1); hypertensive nephropathy (1); Infertility (1); liver cirrhosis (1); lymphoid neoplasm (1); malignant glioma (1); melanoma (1); Meniere disease (1); neurological disorders (1); oligodendroglioma (1).
A further 9 diseases each share a sentence with ZBTB20 in 1 paper.